H1-10 (H1.10 linker histone)
Description:
Histone H1 protein binds to linker DNA between nucleosomes forming the macromolecular structure known as the chromatin fiber. Histones H1 are necessary for the condensation of nucleosome chains into higher-order structured fibers and promote formation of the H3K27me3 mark by the PRC2/EED-EZH2 complex.
Synonyms: H1FX; MGC15959; MGC8350; H1X; H1.10
Tractability: PROTAC: ubiquitination databases record sites on it.
Gene: Protein-coding gene on chromosome 3 (129,314,771 to 129,316,286, reverse strand). Ensembl gene ENSG00000184897.
Subcellular location: Nucleus; Nucleus, nucleolus; Chromosome
Subcellular location (Human Protein Atlas): Nucleoli; Nucleoplasm; Mitotic chromosome; Nucleoli rim
Gene Ontology:
Molecular function: cadherin binding; RNA binding; structural constituent of chromatin; double-stranded DNA binding; nucleosomal DNA binding; DNA binding
Biological process: chromosome condensation; negative regulation of DNA recombination; nucleosome assembly
Cellular component: chromosome; nucleolus; nucleoplasm; nucleus; nucleosome
Genetic constraint (gnomAD): Loss-of-function variants: 0 observed, 0.53 expected, observed/expected ratio (o/e) 0, 90% interval 0 to 1.83. That is too few expected variants to judge how well the gene tolerates losing a copy. Missense variants: 307 observed, 230.18 expected, observed/expected ratio (o/e) 1.33, 90% interval 1.21 to 1.47. Synonymous variants: 191 observed, 120.45 expected, observed/expected ratio (o/e) 1.59, 90% interval 1.41 to 1.79.
Homologues: Orthologues: chimpanzee H1-10 (99% identical), macaque H1-10 (99% identical), pig H1-10 (90% identical), dog H1-10 (89% identical), mouse H1f10 (67% identical), rat H1f10 (64% identical), guinea pig H1-10 (59% identical), tropical clawed frog rbm43l (57% identical), zebrafish h1-10 (44% identical), Caenorhabditis elegans hil-3 (32% identical), Caenorhabditis elegans hil-5 (30% identical), Caenorhabditis elegans hil-2 (29% identical), and 2 more. Paralogues in human: H1-0 (30% identical), H1-2 (30% identical), H1-4 (30% identical), H1-5 (30% identical), H1-3 (28% identical), H1-1 (28% identical), H1-6 (22% identical), H1-8 (20% identical), H1-7 (17% identical).
Diseases named in the same sentence as H1-10 in open-access papers:
H1-10 is named in the same sentence as 10 diseases in open-access papers, as found by Europe PMC text mining. Sharing a sentence is not in itself a finding about the gene and the disease.
H1-10 shares sentences with these, for which no sentence is quoted: cancer (4 papers); tumor (4); neuroendocrine tumors (3); adenocarcinoma (1); Anxiety (1); breast carcinoma (1); Cornelia de Lange syndrome-4 (1); glioma (1); infection (1); malaria (1).